INS (insulin)
Diseases named in the same sentence as INS in open-access papers (continued):
Sharing a sentence is not in itself a finding about the gene and the disease.
diabetes (continued). "Flaxseed, an excellent source of omega fatty acids, has been shown to decrease serum glucose and insulin levels in overweight/obese individuals with pre-diabetes after 12 weeks of consumption." (PMID 40216734, 2025). "Supplementary analyses included chronic disease medicines (diabetes, hypertension, and insulin), distribution trends of Jan Aushadhi Kendras (2018–2022), and global benchmarking using WHO indicators." (PMID 41426670, 2025). "Diabetes mellitus is a complex group of metabolic diseases characterized by persistent hyperglycemia due to disordered insulin secretion, insulin action, or both, with etiologic heterogeneity at the molecular level according to classification." (PMID 41246639, 2025). "These advancements underscore the method’s dual industrial and therapeutic value, exemplified by insulin’s century-long role in diabetes management and the recent development of Fc-fusion therapeutics with extended half-lives." (PMID 40507941, 2025). "Another study verified that insulin pump therapy offers potential advantages for diabetes management." (PMID 41146752, 2025). "The class was conducted in a hybrid format consisting of a simulation of providing nursing care to a patient with diabetes and an on-demand lecture on blood sugar regulation, insulin secretion, and action." (PMID 41220562, 2025). "Stage 2 is characterised by glucose intolerance or dysglycaemia, while stage 3 T1DM is characterised by the biochemical criteria for diabetes in asymptomatic (stage 3a) or symptomatic people (stage 3b) who will require insulin therapy." (PMID 41157252, 2025). "It is also accepted that connected insulin pens and the data extracted from them have limitations, and that future development will increase their role in technology‐driven models of diabetes care." (PMID 41039947, 2025). "The EGIR emphasizes elevated plasma insulin alongside two metabolic abnormalities, excluding those with diabetes, while the IDF requires central obesity plus any two of four other risk factors." (PMID 40969606, 2025). "Key strategies include increasing investments in diabetes education, preventive care, and ensuring affordable access to insulin therapy, which are essential for reducing the incidence of kidney-related complications." (PMID 40166677, 2025). "These agonists can improve insulin signaling, regulate glucose and lipid metabolism, and offer protection against Type 2 diabetes mellitus (T2DM) by stimulating AMPK activity in adipose tissue, liver, and muscle, irrespective of PPARγ activation." (PMID 40430476, 2025). "Diabetes is a group of chronic metabolic disorders marked by persistent hyperglycemia due to defects in insulin secretion, action, or both." (PMID 41010974, 2025). "In contrast, the use of diabetes course and insulin use time to measure the long-term chronic effects of diabetes on the body is more stable and objective." (PMID 40616074, 2025). "Prior studies have demonstrated that amino acid substitutions at the B22 position can lead to a spectrum of diabetes phenotypes, ranging from mild forms of Maturity-Onset Diabetes of the Young (MODY) to severe insulin-deficient neonatal diabetes." (PMID 40305339, 2025). "Due to its impact on insulin sensitivity, oxidative stress, and glucose metabolism, N. sativa has been found to be a potentially valuable natural product for diabetes." (PMID 40842670, 2025). "In this study, we have shown that continuous insulin infusion, compared with bolus administration in patients with diabetes after CABG, promotes better control of postoperative glycemia." (PMID 40364261, 2025). "The development of diabetes mellitus is considerably influenced by insulin resistance, which stems from abnormalities in insulin-mediated glucose uptake and/or glucose release in peripheral tissues, liver, and muscles." (PMID 39791169, 2025). "Effectively managing diabetes involves a combination of medications, insulin therapy, and self-management training." (PMID 39563945, 2025).
diabetes (continued). "Diabetes mellitus encompasses a group of metabolic diseases characterized by chronic hyperglycemia resulting from defects in insulin secretion, insulin action, or both." (PMID 40710568, 2025). "Automated insulin delivery systems, which detect real-time blood glucose levels and self-adjust insulin delivery rates, have long been a goal in the management of diabetes." (PMID 40718205, 2025). "Continuous glucose monitoring (CGM) is a significant advance for diabetes management that, while standard of care for management of type 1 diabetes mellitus, is increasingly used for insulin-treated patients with type 2 diabetes mellitus." (PMID 40057678, 2025). "Background and Objectives: Type 2 Diabetes Mellitus (T2DM) is a metabolic disease caused by the failure of the skeletal muscle, liver and adipose tissue to respond to insulin." (PMID 40142334, 2025). "Diabetes management tools such as blood glucose monitoring, insulin pump use, andintensive education on proper management reduce the risk of DKA." (PMID 40893024, 2025). "Changes in glycemic and metabolic parameters in individuals with type 2 diabetes mellitus (T2DM) following initiation of insulin degludec/aspart (IDegAsp)." (PMID 41293743, 2025). "Our study tracked and compared changes in indices representing β-cell function and insulin sensitivity through periods of menopausal transition in four groups according to the onset and timing of incident diabetes." (PMID 40361840, 2025). "Because of this, people with diabetes need to receive injectable insulin multiple times a day to control their blood sugar levels." (PMID 40574088, 2025). "Cer is known to mediate lipotoxicity, contributing to inflammation, impaired insulin signaling and apoptosis, which promotes CVD risk factors, such as hypertension, diabetes, dyslipidemia and kidney disease." (PMID 40980166, 2025). "For example, mRNA vaccines can be engineered to produce insulin for diabetes patients or to replace defective proteins in genetic disorders." (PMID 40144393, 2025). "Diabetes mellitus is a group of metabolic disorders characterized by chronic hyperglycemia resulting from impaired insulin secretion, insulin action, or both." (PMID 41155632, 2025). "Initially, in pre-DSEP training, the majority of diabetes knowledge was poor to fair, with the lowest in areas of insulin therapy, glucose monitoring, and diabetic foot exams." (PMID 40126315, 2025). "Calculations based on the ipITT revealed a nearly fourfold increase in the area under the curve in diabetes compared to the control group, indicating a significant slowdown in glucose uptake by peripheral tissues as a result of insulin resistance." (PMID 40776976, 2025). "Continuous Subcutaneous Insulin Infusion (CSII), also known as insulin pump therapy, has emerged as a key advancement in diabetes care, offering improved glycemic variability, lifestyle flexibility, and reduced hypoglycemic episodes." (PMID 40887640, 2025). "Through the integration of MeRIP-seq and RNA-seq, we identified the intersection genes of differentially expressed genes in m6A modification sites and differential mRNAs in people with diabetes before and after intensive insulin therapy." (PMID 40299682, 2025). "Diabetes is a chronic and progressive metabolic disorder characterized by hyperglycemia due to impaired insulin secretion, insulin action, or both." (PMID 40332318, 2025). "The results from KEGG suggest that these differential genes are involved in synapse vesicle recycling, insulin secretion, diabetes, and other pancreas-related functions." (PMID 41132793, 2025). "During the occurrence and development of diabetes, the damage of islet β cell function gradually progresses from reversible to irreversible, insulin secretion is reduced, and diabetes and its complications are gradually aggravated." (PMID 41181709, 2025).
diabetes (continued). "Firstly, the inclusion of diabetes-related input variables for the DL models, such as insulin, physical activity and carbohydrates intake, that would likely improve prediction performance." (PMID 40585404, 2025). "In Diabetes Mellitus (DM), a metabolic disorder characterized by elevated blood glucose due to impaired insulin action, platelet function is dysregulated and contributes to the pathological progression of the disease." (PMID 41302143, 2025). "Specifically, the LHRH analogue group demonstrated higher fasting glucose levels, basal insulin levels, and HOMA-IR (Homeostatic Model Assessment for Insulin Resistance) scores, indicating an elevated risk of diabetes." (PMID 41070109, 2025). "Their mammalian‐like ghrelin and leptin activity regulates lipid storage and metabolism, and their insulin‐producing cells share signaling pathways with mammals, making zebrafish suitable for mimicking diabetes." (PMID 41030912, 2025). "These factors—along with differences in insulin resistance, insulin secretion capacity, and the presence of comorbidities—contribute to the heterogeneity of diabetes and its related complications." (PMID 40310669, 2025). "further refined this ischaemic stroke risk prediction model by focusing on history of prior stroke, diabetes treated with insulin and NT‐proBNP levels, using data from three contemporary HF trial cohorts." (PMID 39552607, 2025). "The second type of DM is type 2 diabetes mellitus (T2DM) resulting from insulin resistance or impaired insulin action in peripheral tissues (liver, skeletal muscles and adipose tissues) and pancreatic beta cell dysfunction." (PMID 40572705, 2025). "This is especially true with patients with diabetes mellitus who have poor regulation of insulin, meaning that they will require intensive preoperative, intraoperative, and postoperative care." (PMID 40519247, 2025). "Disposition index reflects the hyperbolic relationship between insulin secretion and sensitivity, with a reduced disposition index indicating a closer path towards diabetes." (PMID 39422718, 2025). "HbA1c is also recognized as a simple and useful marker for accurately predicting insulin sensitivity in diabetes patients." (PMID 40286055, 2025). "One study reported an 87% reduction in oral diabetes medication use and a 79% reduction in insulin use after surgery." (PMID 40895654, 2025). "Diabetes is one of the most common chronic diseases characterized by abnormal hyperglycemia resulting from defects in insulin secretion or insulin action, which is distributed all over the world, especially in developing countries." (PMID 39817378, 2025). "Most patients with ketosis-prone diabetes become insulin independent and their pathology can be managed utilizing diet alone or in association with oral antidiabetics." (PMID 40710886, 2025). "In studies targeting diabetes treatment, insulin secretion was a primary endpoint, assessed in 80 % of the 36 investigations in this category." (PMID 40547419, 2025). "The lncRNA, MEG3, which regulates the insulin signaling pathway implicated in the molecular mechanism of T3D, may be a molecular therapeutic target for managing the onset of complications and the advancement of the disease brought on by diabetes and Alzheimer’s disease." (PMID 40869265, 2025). "Various drug classes have been identified that enhance insulin sensitivity in patients with prediabetes or diabetes mellitus, including biguanides, thiazolidinediones, GLP-1 receptor agonists, and SGLT2 inhibitors." (PMID 40564010, 2025). "Among 4401 participants, 2884 (65.5%) were receiving insulin at baseline; these participants were more likely to have lower estimated glomerular filtration rate, higher albuminuria and a longer duration of diabetes (all P < .001)." (PMID 40036884, 2025). "Inducing the neogenesis of pancreatic insulin-producing β cells holds great promise for diabetes research." (PMID 40339569, 2025).
diabetes (continued). "Diabetes can be broadly classified into two types: Type 1 diabetes (T1D), where the body’s immune system destroys insulin-producing beta cells in the pancreas, and Type 2 diabetes (T2D), characterized by insulin resistance and eventual beta cell dysfunction." (PMID 40352348, 2025). "This is consistent with our participants perceptions that one’s use of insulin means their diabetes has worsened (71.4% of participants) and that they are seen as sicker in the community than others (34.4%)." (PMID 40336418, 2025). "Behaviors that are visible in the management of diabetes—such as blood glucose measurements, insulin injections, and dietary restrictions—can stigmatize these children among their peers and make them targets for bullying and social discrimination." (PMID 40447901, 2025). "Diabetes is a chronic metabolic illness defined by a constant rise in blood sugar levels due to failure in insulin secretion and the absorption mechanism." (PMID 40574088, 2025). "The most common type of diabetes treatment reported was oral medications only (n = 221, 61.4%), while a quarter of the participants used insulin only (n = 91, 25.3%)." (PMID 40666264, 2025). "Adherence assessment and counselling by diabetes care providers on therapy-related barriers including how to deal with side effects and forgetfulness must be continually offered to patients on insulin therapy to secure their greater adherence." (PMID 39854487, 2025). "This is a serious complication of diabetes that develops when the body cannot produce enough insulin, thereby breaking down fat as fuel and resulting in a buildup of acids (ketones) in the bloodstream." (PMID 40760593, 2025). "Insulin was introduced in 1921, and its annual sales are also steadily increasing due to an increased prevalence of diabetes and obesity, reaching 10%." (PMID 40006605, 2025). "Diabetes management relies on real-time data from medical devices, such as continuous glucose monitors (CGMs), insulin pumps, and hybrid closed-loop systems." (PMID 40152409, 2025). "Diabetes mellitus (DM) is a chronic metabolic disorder characterised by dysfunctional insulin secretion, insulin resistance, or a combination of both, resulting in dysregulated blood glucose levels." (PMID 41186211, 2025). "Diabetes Mellitus (DM) is a chronic metabolic and endocrine disorder characterized by persistent hyperglycemia resulting from defects in insulin secretion and/or action." (PMID 40786180, 2025). "Four patients subsequently developed diabetes, requiring insulin therapy at 5 years, 13 years, and 15 years, respectively." (PMID 40256398, 2025). "In diabetes, insulin resistance and dysregulation disrupt brain insulin signaling, impairing neuronal function and cognition." (PMID 39822993, 2025). "Diabetes mellitus is characterized by elevated blood sugar levels resulting from disruptions in insulin function, secretion, or both." (PMID 40075856, 2025). "Our Chinese‐specific prediction models incorporated lipid indices and fasting C‐peptide, while variables such as family history of diabetes, HbA1c, use of glucose‐lowering drugs or insulin, and time to insulin therapy were excluded." (PMID 40966384, 2025). "For early diagnosis of diabetes and MS, simpler and less invasive tests, such as blood glucose measurements and assessments of insulin levels or glycated hemoglobin, are more suitable and accessible for widespread use." (PMID 40556851, 2025). "Variations in gut motility and absorption rates are particularly important when developing therapeutics like insulin for diabetes." (PMID 41477339, 2025). "In diabetes care, digital twins are being tested to model the impact of lifestyle changes or insulin adjustments on long-term HbA1c control, cardiovascular disease risk, and complication rates." (PMID 41282582, 2025).
diabetes (continued). "According to extensive research in mammals, diabetes typically results from either a failure of the pancreas to produce enough insulin or a reduction in insulin sensitivity, also known as insulin resistance." (PMID 41160608, 2025). "Type 1 diabetes mellitus (T1DM) is characterized by progressive β-cell death, leading to β-cell loss and insufficient insulin secretion." (PMID 39901210, 2025). "This study reveals substantial disparities in the accessibility and reimbursement of diabetes technologies and insulin for children with T1D, depending on their continent and country of residence." (PMID 40864470, 2025). "Diabetes is marked by metabolic chaos, resulting in chronic hyperglycemia and compromised insulin signaling." (PMID 40469683, 2025). "In the management of diabetes, insulin therapy typically combines rapid-acting and long-acting insulin formulations to address both postprandial glucose spikes and basal insulin requirements." (PMID 40510890, 2025). "In pancreatic β-cells, HNF4A plays a crucial role in insulin secretion and β-cell survival, making it an important factor in diabetes pathophysiology." (PMID 40926269, 2025). "Studies have shown that EDEM2 silencing decreases SLC2A2 and PXD1 expression, leading to impaired insulin secretion, and that it is involved in early childhood diabetes." (PMID 39535371, 2025). "The study highlighted the inadequacy of threshold methods like Hutchison’s heuristic for diabetes Type-1 patients due to the influence of insulin interventions." (PMID 40847068, 2025). "Diabetes mellitus (DM) is a chronic metabolic disorder characterized by persistent hyperglycemia resulting from impaired insulin secretion, insulin resistance, or both." (PMID 40426934, 2025). "The National Diabetes Inpatient Audit Report 2019 underscores a concerning trend: rising medication errors, insulin errors, and hospital acquired DKA." (PMID 39957319, 2025). "Type 2 diabetes mellitus (T2DM), which represents over 90% of DM cases, is primarily characterized by insulin resistance and a relative deficiency in insulin secretion." (PMID 40941992, 2025). "This was achieved through the analysis and six-month follow-up of patients with type 1 diabetes mellitus who used insulin pump therapy, comparing their results with those from the same patients during a period when they were on MDI insulin therapy." (PMID 41146752, 2025). "In IRS1- or IRS2-knockout mice, the peripheral tissues of the mice exhibit insulin resistance due to the blockage of PI3K/AKT signaling, and the impairment of insulin secretion further contributes to the development of diabetes mellitus." (PMID 40747301, 2025). "If diabetes is confirmed by the results of the oral glucose tolerance test, the question arises of how to treat it with insulin." (PMID 39874570, 2025). "Turrin and Trujillo further emphasized that many patients undergoing insulin pump therapy face challenges related to diabetes numeracy, particularly older individuals and those with higher A1c levels." (PMID 40566297, 2025). "Current diabetes treatments, such as oral hypoglycemic agents and insulin, have shortcomings, including hypoglycemia, increased body mass, and additional complications, underscoring the need for new antidiabetic targets and glycemic control strategies." (PMID 40549787, 2025). "Over the past 2 decades, increasing genetic and biological evidence has indicated that multiple factors can affect these early events of INS biosynthesis, and defects in these events can lead to cell failure and diabetes both in humans and animal models." (PMID 40392602, 2025). "Especially, longitudinal studies on a large group of participants are needed in assessing the effects of various insulin analogues and insulin-sensitizing drugs on bone health, with implications for individuals with diabetes." (PMID 40725728, 2025).